ALB (albumin)
Diseases named in the same sentence as ALB in open-access papers (continued):
Sharing a sentence is not in itself a finding about the gene and the disease.
lymph node metastasis (continued). "The constructed nomogram included lymph node metastasis, liver metastasis, carbohydrate antigen 19-9, carcinoembryonic antigen, albumin, and C-reactive protein." (PMID 38057434, 2023). "Age, BMI, NRS2002 nutritional risk score, lymph node metastasis, TNM staging, tumor diameter, lymphocyte count, serum albumin, and serum creatinine were included in the ordinal logistic regression." (PMID 37182137, 2023). "These variables were further used in multivariate Cox analysis, and age, stage, histopathological subtype, lymph node metastasis, NLR, MLR, fibrinogen, albumin and blood type were significantly associated with both OS and PFS." (PMID 38031022, 2023). "Univariate analysis revealed that FIGO stage, tumor size, lymph node metastasis, parametrial invasion, depth of invasion, radiotherapy, chemotherapy, albumin, lymphocytes, neutrophils, and LANR were significantly associated with OS (p<0.05)." (PMID 37729271, 2023). "Patients in the LW group had significantly lower serum albumin, greater tumor depth, and more advanced lymph node metastases than those in EW group." (PMID 35932031, 2022). "Elevated CA19-9 was associated with decreased albumin levels, more advanced BCLC staging and AJCC staging, and the presence of lymph node metastasis (p < 0.05)." (PMID 36556261, 2022). "Univariate analysis of OS indicated that age, gender, albumin, eGFR (severe CKD), total gastrectomy, depth of tumor, lymph node metastasis, complications (CD ≥ 3) and blood loss estimates (≥ 100 mL) were predictors of OS." (PMID 33930090, 2021). "Univariate analysis showed that factors affecting the prognosis of colon cancer included CEA, lymph node metastasis, peripheral nerve invasion, vascular invasion, albumin, peripheral blood lymphocytes, CEA/PNI, operation mode and postoperative chemotherapy." (PMID 34355011, 2021). "Univariate analysis identified ALB, DB, CA19-9, differentiation, and portal vein system invasion as the risk factors for lymph node metastases." (PMID 33032609, 2020). "In the univariate analysis, curability, GOO, age, prealbumin, albumin, hemoglobin (Hb), the tumor size, the macroscopic type, lymph node metastasis, and the depth of invasion had a statistically significant influence on prognosis." (PMID 32774358, 2020). "None of the clinical-pathological features was notably related to the PDW including gender, age at diagnosis, pathology grade, lymph node metastasis, pathological stage, vessel invasive, treatment regimen, albumin, fibrinogen, and hemoglobin." (PMID 31645619, 2019). "This showed that albumin <3.9 g/dL, lymph node metastasis, solid component diameter > 20 mm, and postoperative complications were statistically significant independent risk factors." (PMID 31436042, 2019). "In later stages of lymph node metastasis, when the tumor begins to invade vascular and neural tissues, the albumin level (> 43.1 g/L) is likely to be an important predictor that indicates and promotes skip metastasis." (PMID 31088404, 2019). "Univariate analysis of OS using the Cox proportional hazards model identified the poor prognostic factors as follows: lymph node metastasis, incomplete AC, and low postoperative serum albumin level." (PMID 27442667, 2016). "The reason that PNI could be used as a prognostic factor for lymph node metastasis in GC lies in the fact that PNI was calculated from serum albumin concentration and peripheral blood lymphocyte count." (PMID 40297178, 2025). "In patients aged < 75 years, independent prognostic factors identified by univariate and multivariate analyses included lymph node metastasis (hazard ratio [HR], 1.598; p = 0.007), tumor size (HR, 1.489; p = 0.043), R status (HR, 1.536; p = 0.011), and serum albumin levels (HR, 1.526; p = 0.031)." (PMID 39950748, 2025). "In our case, lymphocyte–CRP and CRP–albumin ratios also changed and may therefore also predict lymph node metastasis in GBM." (PMID 37794336, 2023).
lymph node metastasis (continued). "Univariate analysis revealed that tumor grade, FIGO stage, tumor size, lymph node metastasis, parametrial invasion, lympho-vascular space invasion, depth of invasion, radiotherapy, chemotherapy, albumin, lymphocytes, neutrophils, and LANR were all significantly associated with PFS (p < 0.05)." (PMID 37729271, 2023). "The univariate analysis of postoperative complications showed that there were significant differences in age, gender, NRS2002 nutritional risk score, PNIS, depth of tumor invasion, lymph node metastasis, TNM stage, hemoglobin, lymphocyte count, albumin, and serum creatinine." (PMID 37182137, 2023). "The high PLR was associated with tumor diameter, advanced tumor invasion, lymph node metastasis, advanced TNM stage, tumor location, total gastrectomy, low hemoglobin level, low albumin level, high fibrinogen level, high platelet level, and high NLR (all P′s < 0.05)." (PMID 33997045, 2021). "In the univariable COX regression analysis, parameters including age, tumor size, menopausal status, pathological grade, FIGO stage, lymph node metastasis, ascites, CTC counts, M-CTC percentage, albumin level, CA-125 and HE4 were significantly associated with ovarian cancer recurrence." (PMID 33753862, 2021). "A high PLR was associated with larger tumor size, advanced tumor invasion, lymph node metastasis, advanced TNM stage, tumor location, total gastrectomy, low hemoglobin level, low albumin level, high fibrinogen level, high platelet level, and high neutrophil-to-lymphocyte ratio (NLR, all P′s < 0.05)." (PMID 33997045, 2021). "The univariable analysis demonstrated that BMI, jaundice, lymph node metastasis, intrahepatic involvement, extrahepatic involvement, tumor differentiation, radical cure, R0, TG, HDL, TC/HDL, TG/HDL, ApoA1, ApoB, lipoprotein, albumin, GGT, ALP, TBIL, CA199 were associated with OS (P < 0.05)." (PMID 33036576, 2020). "Additionally, Cox regression survival analysis showed lower albumin (<3.9 g/dL), lymph node metastasis, larger solid component diameter (>20 mm), and postoperative complications were independently associated with poor prognosis." (PMID 31436042, 2019). "Poor DFS was significantly associated with CCI ≥ 3, albumin <3.9 g/dL, prognostic nutritional index < 40, nonadenocarcinoma cancer, lymph node metastasis, solid component diameter > 20 mm, and postoperative complications (all P < 0.05, log‐rank test)." (PMID 31436042, 2019). "We demonstrated that a low preoperative PNI value was associated with age, BMI, white and red blood cell counts, a large tumor size, deep invasion, lymph node metastasis, an advanced pStage, lower albumin concentrations, and higher C-reactive protein levels, but not preoperative serum CEA levels." (PMID 29534689, 2018). "Multivariate analyses revealed that age, tumor size, lymph node metastasis (LNM), lymphovascular invasion (LVI), urea nitrogen, creatinine, and the albumin/fibrinogen ratio (AFR) were independent predictors for OS." (PMID 40678059, 2025). "Univariate Cox regression analysis identified higher Child-Pugh scores, lower levels of serum ALB, levels of CRP>10 mg/L, the presence of lymph node metastasis and distant metastasis, late TNM stage and recurrent tumor as risk factors." (PMID 40666526, 2025). "Independent risk factors associated with satisfactory tumor reduction in patients with ovarian cancer undergoing debulking surgery included decreased albumin levels, ALP > 137 U/L, ECOG = 1 score, HE4 > 140 pmol/L, and lymph node metastasis." (PMID 39050577, 2024). "Parameters showing variance included albumin and alkaline phosphatase (ALP) levels, ECOG score, CA125, HE4, FIGO staging, and lymph node metastasis." (PMID 39050577, 2024). "Single-factor analysis revealed the significance of factors such as albumin levels, alkaline phosphatase (ALP), ECOG scores, CA125, HE4, and lymph node metastasis." (PMID 39050577, 2024).
lymph node metastasis (continued). "The present nomogram contains 6 variables (lymph nodes metastasis, liver metastasis, CA19-9, CEA, albumin, and CRP), all of which are commonly used in daily medical practice." (PMID 38057434, 2023). "Among medical features, five variables, including tumor differentiation, T-stage, lymph node metastasis (LNM), albumin-to-fibrinogen ratio (AFR), and carbohydrate antigen 19-9 (CA19-9), were used to develop machine learning models." (PMID 37007095, 2023). "The group with a high CRP/albumin ratio (>0.085) had a higher clinical stage of TNM (p = 0.002) and larger primary tumors (p = 0.029) with statistically significant differences in lymph node metastasis and distant metastasis." (PMID 33066436, 2020). "Ten factors were related to PRS: serum CA19-9, platelet count, tumor size, tumor number, lymph node metastasis, time to recurrence, number at recurrence, serum CA19-9 at recurrence, albumin-bilirubin (ALBI) grade at recurrence, and treatment allocation." (PMID 32300559, 2020). "In univariate analysis, lymph node metastasis, PDW (categorical variable), albumin, and clinical stage were significant predictors of OS." (PMID 28592835, 2017). "Platelets counts were significantly correlated with FIGO stage, lymph node metastasis, present of ascites, high CA125 levels, decreased albumin levels, and platinum resistance." (PMID 28498842, 2017). "We investigated whether there is a relationship between the hemoglobin, albumin, lymphocyte, and platelet (HALP) score and PTC central region lymph node metastasis in the preoperative period." (PMID 39897301, 2025). "Specifically, in patients aged < 75 years, independent prognostic factors included lymph node metastasis, tumor size, serum albumin levels, and R status, with no violations of the proportional hazards assumption confirmed by Schoenfeld residual tests." (PMID 39950748, 2025). "The purpose of this study is to investigate the predictive significance of (platelet × albumin)/lymphocyte ratio (PALR) for lymph node metastasis (LNM) in patients with clinically node-negative colon cancer (cN0 CC)." (PMID 37081978, 2023). "The backward elimination procedure in the Cox regression analysis identified 6 factors (lymph node metastasis, liver metastasis, carbohydrate antigen 19-9 [CA19-9; log scale], carcinoembryonic antigen [CEA; log scale], albumin, and C-reactive protein [CRP; log scale]) in the training set." (PMID 38057434, 2023). "In contrast, age, sex, albumin, surgical margin status, hormonal function, tumor location, lymph node metastasis, and lymphatic invasion were not significant predictors of recurrence." (PMID 33789657, 2021). "By comparing G-NET patients with or without LNM, we found that older age, preoperative lower albumin level, higher CEA level, higher INR, longer TT, higher Ki67, and CgA positive rate were associated with lymph node metastasis." (PMID 33789664, 2021). "The frailty group showed an older age, lower serum albumin concentration, lower prognostic nutritional index, larger tumor diameter, and higher rate of lymph node metastasis than the non-frailty group (p < 0.05)." (PMID 33781262, 2021). "For OS, the significant inferior prognostic factors included the male sex, history of alcohol consumption, ALT, AST, TBil, ALB, ALP, GGT, WBC, NC, LC, NLR, Cr, PTA, AFP ≥ 400 ng/mL, tumor number ≥ 3, tumor diameter ≥ 5 cm, lymph node metastasis, and portal vein involvement (p < 0.05)." (PMID 28143427, 2017).
lymph node metastasis (continued). "In a study analyzing biopsy and blood samples from EC patients, albumin-corrected serum calcium levels were significantly higher than in controls (p < 0.05) and positively correlated with lymphovascular space invasion (LVSI), lymph node metastasis, myometrial invasion, and cervical involvement." (PMID 41140697, 2025). "Age, sex, albumin, pre-albumin, CRP, ferritin, CRP/Albumin ratio, tumor size, differentiation grade, lymph node metastases, perineural invasion, or vascular invasion were not statistically related with FR + CTC in our study." (PMID 38037003, 2023).
delirium (106 papers, 2014 to 2026). A disorder characterized by confusion; inattentiveness; disorientation; illusions; hallucinations; agitation; and in some instances autonomic nervous system overactivity. "Meanwhile, malnutrition emerged as a major risk factor for delirium in elderly patients, with serum albumin being an important predictor of delirium." (PMID 38263028, 2024). "Albumin (OR 2.39, CI 1.11-5.14, P=0.02) and steroids (OR 2.17, CI 1.06-4.40, P=0.03) were found to be risk factors for delirium." (PMID 39679665, 2024). "The association between increased risk of dysphagia and delirium was found to be partially mediated by serum albumin, accounting for approximately 10% (95%CI: 4-19%, p < 0.001) of the mediation." (PMID 38263028, 2024). "To further examine the association between dysphagia and adverse outcomes, particularly delirium, we conducted a causal mediation analysis using serum albumin levels measured during the patient’s initial admission to the ICU as a mediating factor." (PMID 38263028, 2024). "In our study, we also made a significant discovery regarding the partial mediation of serum albumin levels in the association between dysphagia and delirium (ACME: 0.02, 95% CI: 0.01 to 0.03; p < 0.001)." (PMID 38263028, 2024). "A meta-analysis of risk factors for the onset of delirium among elderly patients in the medical ICU showed that a low albumin level is associated with delirium." (PMID 38131687, 2023). "Age, dementia, severe illness, poor vision, urinary catheters, polypharmacy, and low albumin are known risk factors for delirium and in recent years, frailty is increasingly being recognised as a risk factor." (PMID 36683168, 2023). "Low albumin levels were associated with postoperative mortality, ED visits, postoperative delirium, and prolonged hospital or postoperative stay." (PMID 37955965, 2023). "Recent studies have reported the association between albumin level and delirium, and meta-analysis of risk factors of delirium occurrence among elderly patients in medical ICUs has found that low albumin level is associated with delirium." (PMID 36937934, 2023). "The performance status (p = 0.02), preoperative albumin level (p = 0.02), and age 75 years or older (p = 0.02) were significantly associated with postoperative delirium." (PMID 37232788, 2023). "Further parameters, such as blood pressure, albumin levels, anesthesia drugs, perioperative hypotension, and hypoxemia, were also investigated as possible factors increasing the risk of delirium, with contradictory results." (PMID 35804948, 2022). "In this study, we identified that CIRS and preoperative albumin levels were also associated with postoperative delirium." (PMID 36405895, 2022). "The CIRS and preoperative albumin levels were also independently associated with postoperative delirium." (PMID 36405895, 2022). "Multivariate logistic regression analysis revealed that intraoperative sedation, age, preoperative albumin level, and hip surgery were significantly associated with the incidence of postoperative delirium." (PMID 33401537, 2021). "Other studies have shown that the increase of preoperative CRP and the decrease of preoperative total protein, albumin, and hemoglobin are independent risk factors for postoperative delirium, which contradicts our conclusions." (PMID 34901277, 2021). "In the subgroup analysis of patients under age 68, only preoperative EF, level of albumin, and C-reactive protein were associated with postoperative delirium by univariable analysis." (PMID 33189145, 2020). "Nevertheless, albumin levels are more frequently monitored in malnourished patients who are at risk of developing delirium." (PMID 32570290, 2020). "Low hematocrit, low hemoglobin, low albumin, and low sodium were the risk factors of delirium (P = 0.011, P = 0.017, P = 0.003, and P = 0.019)." (PMID 33153465, 2020).